CCR2 (C-C motif chemokine receptor 2)
Diseases named in the same sentence as CCR2 in open-access papers (continued):
Sharing a sentence is not in itself a finding about the gene and the disease.
cervical cancer (11 papers, 2010 to 2025). A primary or metastatic malignant neoplasm involving the cervix. "Another team showed that the CCR2-64I variant was associated with a decreased risk of cervical cancer; homozygote carriers of the 64I variant had an odds ratio of 0.31 (0.12–0.77)." (PMID 34833360, 2021). "A statistically significant, association was found with CCR2-64I variant (P = 0.001) and cervical cancer cases and controls after adjusting for ethnicity and smoking." (PMID 20537184, 2010). "Since cervical cancer is a multi-step process which starts with HPV infection it was of interest to determine at which stage the CCR2-64I variant became significant." (PMID 20537184, 2010). "We found a statistically significant association of CCR2-64I variant (P = 0.001) with cervical cancer in African black and mixed-ancestry women adjusted for ethnicity and smoking." (PMID 20537184, 2010). "This study investigated the role of CCR2-V64I polymorphism in cervical cancer, pre-cancers and HPV infection in South African women resident in Western Cape." (PMID 20537184, 2010). "The role of CCR2-V64I polymorphism was investigated in the risk of cancer of the cervix, pre-cancers and HPV infection in South African women of black and mixed-ancestry origin." (PMID 20537184, 2010). "The CCR2-64I variant was significantly associated with cervical cancer when cases were compared to the control group (P = 0.001)." (PMID 20537184, 2010). "When the SIL controls were compared with cervical cancer cases, it was found that CCR2-64I carriers are at more risk of developing cervical cancer (P = 0.001, OR (95% CI) = 6.86 (4.19-11.21)) from SIL." (PMID 20537184, 2010). "There are conflicting reports on the role of the CCR2-V64I polymorphism in the development or risk to cervical cancer." (PMID 20537184, 2010). "Among two studies in Swedish population the first study reported that the CCR2-64I variant was associated with decreased risk of developing cervical cancer." (PMID 20537184, 2010). "Comparing SIL positive controls with the cases showed a significant association of CCR2-64I variant (P = 0.001) with cervical cancer." (PMID 20537184, 2010). "This is the first study of the role of CCR2-V64I polymorphism in cervical cancer in an African population." (PMID 20537184, 2010). "Our study first uncovered that in the hypoxic TME, CCL8 from hypoxia-induced ZEB1-driven cancer cells induced macrophage infiltration mainly into the hypoxic area via the CCR2–NF-κB pathway, and this effect was associated with poor prognosis in cervical cancer." (PMID 31263103, 2019). "Our data suggests that women carrying A allele (P = 0.001, OR (95% CI) = 6.14 (4.79-7.86)) and A/A genotype (P = 0.002, OR (95% CI) = 3.99 (1.68-9.50)) at position 190 of the CCR2 gene have increased risk of cervical cancer compared to women carrying the G variant of it." (PMID 20537184, 2010). "In cervical cancer, it was suggested that CCR2 expression was increased in patient samples with PNI compared to the non-PNI groups." (PMID 39199567, 2024). "SCs migrate to the vicinity of the tumor and secrete CCL2 under signals derived from cervical cancer cells, which acts as a potent chemoattractant, inducing CCR2+ cervical cancer cells to undergo epithelial–mesenchymal transition (EMT) and move along neurites." (PMID 39061654, 2024). "When binding to its receptor CCR2 on the membrane of cervical cancer cells, the CCL2 generated from Schwann cells promoted cancer cell proliferation, migration, and invasion." (PMID 36403055, 2022). "Both CCL2 and its receptor CCR2 have already been described several times in various malignant diseases and there are also corresponding citations for cervical cancer." (PMID 34833360, 2021). "SCs arrive at the site of cancer cells and secrete CCL2 as a strong chemoattractant which then induces CCR2+ cervical cancer cells to move along neurites." (PMID 32064233, 2020).
cervical cancer (continued). "In murine cervical cancers, the depletion of CCR2-dependent TAMs resulted in a compensatory recruitment of pro-tumorigenic tumor infiltrating neutrophils (TINs), that when depleted, impaired the tumor phenotype." (PMID 23372702, 2013). "Based on these results, the CCL2/CCR2 axis may serve as a potential marker for cervical cancer treatment." (PMID 36403055, 2022). "CCL2 expression is a marker of cervical cancer, and enhanced expression of CCR2 may correlate with poor overall survival." (PMID 34464477, 2021). "The results obtained from the cancer genome atlas (TCGA) showed that enhanced expression of CCR2 might correlate with poor overall survival in human cervical cancer." (PMID 32064233, 2020). "CCR2-64I variant showed an increased risk of cervical cancer but not with infection by HPV and pre-cancerous lesions." (PMID 20537184, 2010). "Our results show that CCR2-64I variant is associated with the risk of cervical cancer but does not affect the susceptibility to HPV infection or HSIL in South African women of black and mixed-ancestry origin." (PMID 20537184, 2010). "Moreover, the CCL2/CCR2 axis mediated PNI of cervical cancer in vitro and in vivo." (PMID 32064233, 2020). "SC-derived CCL2 bound to its receptor CCR2 and promoted the proliferation, migration, invasion, and epithelial-mesenchymal transition (EMT) of cervical cancer cells." (PMID 32064233, 2020). "We identified the CCL2/CCR2 axis as a potential marker to predict the PNI and affect the nerve preservation for cervical cancer." (PMID 32064233, 2020). "Although CCL2 is also a ligand of CCR2, we found that CCL8 expression was increased more than CCL2 expression in hypoxic cervical cancer cells, competitively binding with CCR2, which mediated macrophage infiltration." (PMID 31263103, 2019). "Hypoxia increased ZEB1 expression in cervical cancer cells, directly promoting CCL8 production and attracting macrophages via the CCR2–NF-κB pathway." (PMID 31263103, 2019). "Genotyping for CCR2-V64I was done by PCR-SSP in a case-control study of 446 women (106 black African and 340 mixed-ancestry) with histologically confirmed invasive cervical cancer and 1432 controls (322 black African and 1110 mixed-ancestry) group-matched (1:3) by age, ethnicity and domicile status." (PMID 20537184, 2010).
cryptococcal infection (11 papers, 2012 to 2023). "Similarly, CCR2 is required for the recruitment of DCs in response to cryptococcal infection and in CCR2 deficient mice the inflammatory T cell immune response is immediately disrupted." (PMID 25498576, 2015). "Studies with pulmonary cryptococcal infection defined that CCR2 plays a critical role in the egress of monocytes from bone marrow, which in the lungs differentiate into effector IM eliminating C. neoformans." (PMID 34311579, 2021). "The role of CCR2 signaling in pulmonary cryptococcal infections is predominantly protective by promoting protective Th1 antifungal immunity over nonprotective Th2 (22, –, 25)." (PMID 34311579, 2021). "Cryptococcal infection of CCR2−/− mice leads to Th2-type responses, increased lung fungal burden, and decreased recruitment of macrophages and DCs compared to WT mice." (PMID 32117810, 2020). "Our work was assisted by the generation of a CCR2-Cre mouse that will facilitate continued mechanistic evaluation of IM function in cryptococcosis." (PMID 30897162, 2019). "The studies on IM during subacute and chronic cryptococcosis utilized CCR2-/- mice on a BALB/c or mixed C57BL/6 and 129 background with the less virulent C. neoformans serotype D strain 52D." (PMID 30897162, 2019). "MCP1/CCR2 signaling is also responsible for the recruitment of inflammatory DCs and macrophages after cryptococcal infection." (PMID 29403476, 2017). "Lysozyme M (LysM)-cre MHCII fl/fl (macrophages and granulocytes), BATF3−/− (CD103+ conventional dendritic cells), and CCR2−/− (monocytes and monocyte-derived dendritic cells) mice generated robust antigen-specific Th2 responses during cryptococcal infection." (PMID 25764512, 2015). "CCR2-mediated recruitment of monocytes was also shown to be essential for defense against Mycobacterium tuberculosis, Toxoplasma gondii, and Cryptococcus neoformans infection." (PMID 22383883, 2012). "Interestingly, a recent study showed inflammatory monocytes are rapidly recruited to the lung during cryptococcal infection, but depletion of these cells using the CCR2 diptheria toxin receptor (DTR) system leads to improved host survival, reduced pulmonary fungal burden, and reduced dissemination." (PMID 32117810, 2020).
gastric cancer (11 papers, 2016 to 2024). A primary or metastatic malignant neoplasm involving the stomach. "Specifically, “CCR2 on CD14- CD16+ monocyte” was found to have a causal relationship with both stomach cancer and rectal cancer." (PMID 38533503, 2024). "Our present study has proved the prognostic significance of CCR2 expression in patients with gastric cancer, and refined the risk stratification system which based on TNM stage alone." (PMID 26992207, 2016). "CDK5RAP3 reduces the recruitment of circulating monocytes to infiltrate tumour tissue by inhibiting the CCL2/CCR2 axis in gastric cancer." (PMID 35999359, 2023). "Some of these chemokines and receptors, such as CXCL13, CCL4, CCL5, CCR2, CXCR3, and CXCR4, have been experimentally confirmed to be associated with the pathogenesis or prognosis of gastric cancer or other malignancies." (PMID 32685487, 2020). "Compared with the adjacent non-cancerous tissues, significantly higher levels of Ym-1, Fizz-1, arginase-1 and CCR-2, the M2 macrophages’ markers, were observed in gastric cancer tissues with GC-MSCs infiltration." (PMID 31801938, 2019). "CCR2 high expression in the tumor microenvironment is a novel independent unfavorable prognostic factor for patients with gastric cancer." (PMID 26992207, 2016). "But the profound molecular roles of CCR2 and its antagonist in gastric cancer remains far from being fully elucidated and need further research." (PMID 26992207, 2016). "In our present study, we found that CCR2 was highly expressed on the accessory cells around gastric cancer cells and correlated with tumor stage." (PMID 26992207, 2016). "To improve the prognostic accuracy for OS of patients with gastric cancer, we combined CCR2 expression and TNM staging system to generate a predictive model." (PMID 26992207, 2016). "Although we have proved the prognostic significance of CCR2 expression in patients with gastric cancer, especially in those with advanced-stage disease, there are some limitations in our study." (PMID 26992207, 2016). "Multivariate Cox regression analysis identified CCR2 high expression in gastric cancer tissues is an independent poor prognostic factor for patients with gastric cancer." (PMID 26992207, 2016). "CCR2 expression was detected in the accessory cells around gastric cancer cells in a diffused manner." (PMID 26992207, 2016). "This study aims to evaluate the prognostic value of CCR2 expression in patients with gastric cancer after surgery." (PMID 26992207, 2016). "CCR2 expression was confined to the membrane of the accessory cells around gastric cancer cells in a diffused manner, while cancer cells showed negative staining." (PMID 26992207, 2016). "Kaplan–Meier survival analysis and log-rank test were applied to investigate the relationship between CCR2 expression and overall survival (OS) of patients with gastric cancer." (PMID 26992207, 2016). "In summary, our results suggested that CCR2 high expression independently predicts poor postoperative overall survival for patients with gastric cancer." (PMID 26992207, 2016). "Multivariate Cox regression analysis identifies CCR2 high expression was an independent poor prognostic factor for OS of patients with gastric cancer in the two sets (P=0.013 and P=0.006, respectively)." (PMID 26992207, 2016). "Another agent is Sophoridine which has been reported to suppress M2 polarization and increase M1 polarization through TLR4/IRF3 pathway and inhibit TAMs infiltration by downregulating CCR2 expression in gastric cancer TME, thereby improving the cytotoxicity function of CD8 + T cells." (PMID 39003350, 2024). "In gastric cancer tissues, high expression levels of Ym-1, Fizz-1, arginase-1, and CCR-2, as well as a low expression level of iNOS, were verified, and co-localization of GC-MSCs and tumor-associated macrophages (TAMs) was observed by dual immunofluorescence histochemistry." (PMID 31801938, 2019).
gastric cancer (continued). "Taken together, these findings demonstrated that CCR2 high expression could be an independent poor prognosticator for patients with gastric cancer, especially for patients with advanced-stage disease." (PMID 26992207, 2016). "And all these evidences suggest that CCR2 may facilitate gastric cancer progression by recruiting immune suppressive cells into tumor microenvironment to create a tumor-promotive microenvironment." (PMID 26992207, 2016). "In order to investigate CCR2 expression in gastric cancer and explore its potential clinical significance, we determined CCR2 expression levels by immunochemistry in a total of 474 gastric cancer patients with resectable tumor samples (96 in training set and 378 in validation set)." (PMID 26992207, 2016). "But the expression profile of CCR2 in gastric cancer is largely unknown, and its relation with patient outcome remains obscure." (PMID 26992207, 2016). "Incorporation of CCR2 expression with TNM stage system might add some prognostic information for patients with gastric cancer." (PMID 26992207, 2016). "Thus, detailed research on CCR2 expression in gastric cancer is urgently needed." (PMID 26992207, 2016). "In general, the low expression of CDK5RAP3 in gastric cancer can promote the secretion of CCL2, which recruits monocytes to infiltrate the tumour microenvironment through CCL2/CCR2 signalling." (PMID 35999359, 2023). "All these results indicated that the combined CCR2 expression and TNM staging system model show more prognostic power for OS of patients with gastric cancer." (PMID 26992207, 2016). "Furthermore, CCR2 might become a potential immunotherapeutic target for gastric cancer." (PMID 26992207, 2016). "Indeed, some studies in mouse head and neck cancer and gastric cancer have shown PMN-MDSCs and M-MDSCs can be recruited to spleens or tumors of tumor-bearing mice by CXCR2 or CCR2 signaling, respectively." (PMID 37268941, 2023). "Combination of CCR2 expression and TNM stage could provide a better prognostic model for OS of gastric cancer patients." (PMID 26992207, 2016).
Granuloma (11 papers, 2011 to 2025). A compact, organized collection of mature mononuclear phagocytes, which may be but is not necessarily accompanied by accessory features such as necrosis. "Together the findings suggest a critical role for CCR2 in the mobilization of the innate monocyte/macrophage and mDC component of granulomas." (PMID 23444049, 2013). "When type-1 PPD- or type-2 SEA-bead elicited adaptive granulomas were elicited in CCR2 knockout (CCR2−/−) mice, there was impaired monocyte/macrophage recruitment especially during the initial stages of granuloma formation." (PMID 23444049, 2013). "Due to a delay or a lack of immune cell recruitment, CCR2-deficient mice developed loosely formed granulomas; however, the bacterial burden was not greatly impacted." (PMID 36406405, 2022). "This could explain the decrease in the frequency of circulating CD3+ monocytes as they are recruited to the infection site by a CCR2-independent pathway to aid in the formation of granuloma and infection control." (PMID 33977111, 2021). "Moreover, when granulomas were apparent in DT-treated CCR2-DTR mice, they were significantly smaller than those in infected DT-treated WT mice." (PMID 25144366, 2014). "Overall this study suggests that CCL2 and CCL5 may be interacting with mononuclear cells expressing specific CC chemokines receptors (CCL2 → CCR2, CCL5 → CCR1, CCR3, and CCR5) and are important biologically in the formation of pulmonary sarcoidosis granulomas." (PMID 21463523, 2011).
lung adenocarcinoma (11 papers, 2017 to 2025). A carcinoma that arises from the lung and is characterized by the presence of malignant glandular epithelial cells. "The prominent expression of CCR2 in specific clinicopathologic/molecular subgroups of lung adenocarcinomas harboring oncogenic mutations in EGFR and KRAS, as well as in CRCs with microsatellite instability–high status further support the potential for refined patient selection." (PMID 39918395, 2025). "Targeting the C-C Motif Chemokine Ligand 2 (CCL2) and C-C Motif Chemokine Receptor 2 (CCR2) pathways in a lung adenocarcinoma mouse model led to reduced recruitment of M2 macrophages and inhibited tumor growth." (PMID 38545114, 2024). "Factor analysis revealed shared Treg cell-dependent gene programs, foremost, prominent upregulation of VEGF and CCR2 signaling-related genes upon Treg cell deprivation in either setting, as well as in Treg cell-poor versus Treg cell-rich human lung adenocarcinomas." (PMID 37127830, 2023). "Many preclinical studies showed high efficacy of CCL2/CCR2 antagonists, e.g., in the mouse model of lung adenocarcinoma, targeting CCR2 with a small molecule inhibitor not only reduced recruitment of M2-type macrophages but also induced tumor infiltration of activated CD8+ T cells." (PMID 33919517, 2021). "We used LIMMA package to compare the expression differences of CCR2 and CSF2RB in lung adenocarcinoma tumor tissues and normal tissues." (PMID 35574409, 2022). "Altogether, the results presented here indicate that KLRG1, BTK, CCR2 and SCML4 play important roles in the development of lung adenocarcinoma, and their expression can be effective biomarkers to predict LUAD patients’ survival." (PMID 34187403, 2021). "We began our tumor studies by assessing the expression of CCR2 and MCP-1/CCL2 within tumors that developed in syngeneic C57BL/6 mice after subcutaneous injection of a murine lung adenocarcinoma cell line, TC1." (PMID 33322474, 2020). "In this study, through the analysis of the database and clinical samples, we found four markers (KLRG1, BTK, CCR2 and SCML4) which may play important roles in the development of lung adenocarcinoma." (PMID 34187403, 2021). "The current study investigated the anti-proliferative, anti-motile and anti-invasive activities of an antagonist against CCR2, CAS 445479-97-0, by blocking the CCL2/CCR2 axis interaction and downregulating MMP-9 protein expression in human lung adenocarcinoma A549 cells in vitro." (PMID 28424406, 2017). "Here, we investigated the effect of CCR2 antagonist (CAS445479-97-0) on the proliferation, migration and invasion of human lung adenocarcinoma A549 cells by using WST-1 cell viability assay, transwell migration assay, wound healing scratch assay and Matrigel invasion assay." (PMID 28424406, 2017).